EZH2 (enhancer of zeste 2 polycomb repressive complex 2 subunit)
Diseases named in the same sentence as EZH2 in open-access papers (continued):
Sharing a sentence is not in itself a finding about the gene and the disease.
breast cancer (continued). "Further experiments highlighted that SPRY4-IT1 may function as a ceRNA and sponge miRNA and thereby scaffolding target genes in cancers, such as miR-101-3p/EZH2 in cholangiocarcinoma, miR-101-3p/AMPK axis in gastric cancer, and miR-6882-3p/TCF7L2 in breast cancer cell stemness." (PMID 33204703, 2020). "We hypothesized that CDK2-mediated site-specific phosphorylation of EZH2 drives tumorigenesis and contributes to TNBC phenotype, and inhibition of CDK2/EZH2 axis by specific inhibitors may reverse the phenotypes, thereby rendering TNBC targetable by current breast cancer therapies." (PMID 31704972, 2019). "However, EZH2‐only or EZH2/1 inhibition demonstrated no appreciable effect on proliferation of either breast cancer cell line." (PMID 31282094, 2019). "Interestingly, POMT2 positively correlated with EZH2 in breast cancer cells along with non-cancerous cell lines whereas in primary breast tumor and normal breast tissues, a negative correlation existed between the two." (PMID 30760814, 2019). "For example, the lncRNA, nuclear paraspeckle assembly transcript 1 interacted with miR-101 to modulate breast cancer growth by targeting EZH2; the lncRNA, SPRY4 intronic transcript 1 sponges miR-101-3p to promote proliferation and metastasis of bladder cancer cells through up-regulating EZH2." (PMID 31596734, 2019). "Interestingly, compared to control breast cancer cells, selective induction of H3K27me3 but not EZH2 promotes robust spheroid formation and drug resistance against Paclitaxel." (PMID 29460395, 2018). "Overexpression of EZH2 in estrogen receptor negative (ER-) breast cancer promotes metastasis." (PMID 30022044, 2018). "Highly up-regulated in breast cancer, the lncRNA HOX transcript antisense RNA (HOTAIR) mediates H3K27 tri-methylation and the epigenetic silencing of tumor suppressor genes by recruiting enhancer of zeste homolog 2 (EZH2), which is considered a key molecule and potential biomarker for breast cancer." (PMID 29325547, 2018). "While FOXC1 may operate as an anti-metastatic factor in non-BLBC breast cancer subtypes, it was unclear if EZH2-mediated repression of an anti-metastatic program through suppression of FOXC1 was subtype-specific." (PMID 29959321, 2018). "However, the correlation of EZH2 and SMYD3 polymorphisms with breast cancer susceptibility and prognosis has not yet been reported." (PMID 29089464, 2018). "However, a slight increase of H3k4ac and H3k9ac expression on EZH2 promoter was also observed in the in (ER+) cell lines, implying that EZH2 expression could be regulated in part by SIRT1 in different subtypes of breast cancer." (PMID 30093977, 2018). "Furthermore, we revealed that SIRT1 deficiency is associated with substantial induction of acetylated markers on six breast cancer-related gene promoters: AR, BRCA1, ERS1, ERS2, EZH2, and EP300, suggesting an active role of SIRT1 in regulating the expression of these genes in BC." (PMID 30380732, 2018). "In the colorectal and breast cancer models, the lncRNA ANCR suppresses invasion and migration properties by down-regulation of EZH2 via ANCR-mediated CDK1-EZH2 interaction and phosphorylation at Thr 345 and Thr 487 on EZH2, facilitating its ubiquitination and degradation." (PMID 28561778, 2017). "Similarly, Lee ST and colleagues identified that in estrogen receptor (ER)-negative basal-like breast cancer cells, EZH2 binds to a NF-κB component to form a ternary complex, leading to transcriptional activation of its downstream target genes." (PMID 28415635, 2017). "Through the use of a breast cancer (MDA-MB-231) cell assay based on the re-expression of epigenetically silenced genes, we report the identification of hit compounds that phenocopy the effects of dual EZH2/EHMT2 pharmacological inhibition and dual SiRNA gene knockdown." (PMID 26300989, 2015).
breast cancer (continued). "We found that NBAT1 could inhibit the migration and invasion of breast cancer, while the effect of NBAT1 over-expression on invasion was reversed by concomitant EZH2 inhibitors, suggesting that the effect of NBAT1 on cell migration and invasion might be mediated through EZH2." (PMID 26378045, 2015). "Several studies on breast cancer have shown that miR-26a can inhibit cell proliferation, colony formation and migration, as well as promote apoptosis by regulating several carcinogenesis-related processes, including several mechanisms that involve the targeting of MCL-1, MTDH and EZH2." (PMID 25184951, 2014). "In addition, tumor cell growth in soft agar could be suppressed in the breast cancer cell line MCF7 by ectopically expressing RORα, inhibiting EZH2 activity, or silencing VprBP." (PMID 24028781, 2013). "Thus, in breast carcinoma, there is increased HOTAIR expression and increased EZH2 expression." (PMID 23133536, 2012). "In addition, Ezh2 (but not other PcG proteins) was found as a transcriptional activator of c-Myc and cyclin D1 in a breast cancer cell line." (PMID 21624129, 2011). "Thus, the combination of both EZH2 and CDKN1C may be more predictive of breast cancer recurrence than either one alone." (PMID 19340297, 2009). "In comparison, no other CDKN family genes could significantly separate the patients by survival (data not shown), consistent with the hypothesis that these genes might not be targeted by EZH2 in breast cancer." (PMID 19340297, 2009). "In summary, we have demonstrated that DZNep selectively inhibits BRCA1-deficient but not BRCA1-proficient mammary tumor cells, and that this effect is mainly due to the fact that BRCA1-deficient cells are dependent on EZH2, whereas BRCA1-proficient cells are not." (PMID 19709408, 2009). "Moreover, it was reported that under the catalysis of polycomb reactive complex 2 (PRC2), EZH2 can inhibit the transcription of its target gene through the trimethylation of Lys-27 on histone 3 (H3K27me3), thus controlling the expression of FOXC1 in breast cancer." (PMID 40003882, 2025). "EZH2 inhibitors and CM from EZH2 inhibitor-treated cells activated TAMs towards M2 polarization in vitro and in vivo, which might help us understand why EZH2 inhibitors do not achieve benefits in preclinical breast cancer models." (PMID 36038549, 2022). "To clarify the mechanism of epigenetic modification in regulating PDK1 in breast cancer, we address following questions: Firstly, to explore whether PDK1 expression is dysregulated in breast cancer and the aberrant expression of PDK1 is regulated by histone deacetylase 2 (HDAC2) and EZH2." (PMID 35892859, 2022). "However, it is not clear how STAT3 correlates with EZH2 in breast cancer." (PMID 34335938, 2021). "In addition, GEPIA database analysis showed that the mRNA expression levels of EZH2 were significantly higher in breast cancer tissues than normal breast tissues and its expression level was significantly associated with the poorer prognosis of patients in breast cancer." (PMID 34341433, 2021). "Furthermore, EZH2 could increase cancer proliferation and metastasis in many cancer types, including CRC, melanoma, oral squamous cell carcinoma (OSCC), and breast cancer." (PMID 28561778, 2017). "However, no orally bioavailable inhibitors of EZH2 have been used in breast cancer in vivo models." (PMID 26868841, 2016). "Additionally, EZH2 has been found to act as an epigenetic modifier during the TGF-β-induced epithelial-mesenchymal transition (EMT) in breast carcinogenesis and to control the p38 mitogen-activated protein kinase (MAPK) signaling pathway during breast cancer cell migration, invasion and metastasis." (PMID 27092879, 2016). "Thus, the broader outreach of EZH2 may allow it to better activate or influence genes involved in negative estrogen receptor expression breast carcinoma." (PMID 23133536, 2012).
breast cancer (continued). "However, miR-26a did not regulate EZH2 in breast cancer or acute myeloid leukemia cells, indicating that miRNA-regulation of target gene expression may be tissue and/or context specific." (PMID 21941025, 2011). "Positive correlations between ARID1A and PGR expression, and negative correlations between EZH2 and PGR/ESR1 expression, were also observed in breast cancer patient samples." (PMID 35326450, 2022). "Curry and colleagues showed that treatment of the breast cancer cell line MDA-MB-231 with HKMTI-1–005 induced transcription of SPINK1, which did not occur when EZH2 or G9A were individually knocked down." (PMID 35131874, 2022). "In conclusion, our study demonstrated that EZH2 non-canonically methylated and promoted the nuclear localization of pivotal transcriptional factor STAT3 in breast cancer." (PMID 34335938, 2021). "Survival analysis of breast cancer patients up to 4 years (about 1500 days) showed poorer prognosis when expression of both JMJD6 and EZH2 was high, however it did not achieve statistical significance by the end of 5 years." (PMID 33246425, 2020). "To find EZH2 target genes in breast cancer common to both ER positive and ER negative breast cancer we chose MCF-7 and MDA-MB-231 gene expression profiling arrays performed upon EZH2 knockdown." (PMID 30760814, 2019). "Examination of the TCGA dataset further confirmed the negative correlation between EZH2 and CBX6 expression patterns in breast cancer (Spearman r = −0.209, P < 0.0001)." (PMID 30655550, 2019). "A negative correlation existed between EZH2 and its targets except in PMEPA1, which showed a weak positive correlation in breast cancer cell lines." (PMID 30760814, 2019). "Previous studies showed that as a transcriptional inducer, EZH2 functions independently (not as part of the PRC2 complex) in prostate cancer, breast cancer, intestinal cancer and natural killer/T-cell lymphoma (NKTL)." (PMID 28415635, 2017). "In our study, we demonstrated that GSK3β non-phosphorylatable mutant EZH2 (EZH22A, EZH2S363A, EZH2T367A) enhances cell migration and anchorage-independent growth in breast cancer and mammary epithelial cells." (PMID 27494834, 2016). "The breast cancer cell line BT-474, which is the cell line most sensitive to HKMTI-1-005 treatment, has the highest relative expression of EZH2, as detected by Western analysis (data not shown)." (PMID 26300989, 2015). "In contrast, overexpression of EZH2 and BMI1 were reported to have different influences on patient prognosis in breast cancer, and was found to have no prognostic value in urothelial carcinoma of the bladder." (PMID 25243792, 2014). "ZLD1039 is another potent and selective SAM- EZH2 inhibitor, which has not been so widely investigated but has been shown to have concentration-dependent inhibition of PRC2 enzymatic activity against EZH2 in melanoma cells and breast cancer." (PMID 41614754, 2025). "In agreement with these in vitro data, we detected clinical HCMV strains in breast cancer biopsies mostly in luminal breast cancer, but also in some TNBC, with no increase of “oncogenic” markers such as Myc, EZH2, Akt, and Ki67Ag in tumor tissue, and should therefore be referred as LR-HCMV strains." (PMID 36366560, 2022). "The difference of EZH2 and YY1 expression between tumorigenic and nontumorigenic cells could explain the differential inhibitory effects of the two peptides in breast cancer cells and MCF-10A cells." (PMID 34065631, 2021). "However, in the current study we found that SUZ12 was not binding with EZH2, indicating the PRC2-independent action of EZH2 in PDAC as reported in breast cancer." (PMID 34771469, 2021). "In this case, the involvement of JMJD3 is no longer needed, which highlights the existence of non-genomic pathways in the regulation of the BCL2 gene by EZH2, whereas JMJD3 is able to positively regulate BCL2 expression in a genomic way in non-resistant breast cancer cell lines." (PMID 33478063, 2021).
breast cancer (continued). "However, the regulatory relationship between EZH2 and NSD2 and their prognostic values in breast cancer (BC) have not been fully elucidated." (PMID 33665162, 2020). "In qRT-PCR data obtained from MCF-7, T47D, MDA-MB-231 and MDA-MB-453 breast cancer cell lines, a negative correlation was observed between EZH2 and its target gene expression except for PMEPA1 that shared a weak positive correlation with EZH2." (PMID 30760814, 2019). "The overall analysis of clinical samples for EZH2 expression level among smokers and non-smokers led us a hypothesis that EZH2 might have some role in NIC-mediated breast cancer progression." (PMID 29396474, 2018). "First, we found that knockdown of EZH2 by small interfering RNA (siRNA) did not influence the expression of TFIIIC components in neither of the two breast cancer cell lines MCF7 and SUM159, indicating EZH2 could not regulate TFIIIC expression." (PMID 26038315, 2015). "However, in breast cancer metastasis models, particularly in bone, tazemetostat and similar EZH2 inhibitors such as GSK126 have shown limited efficacy, likely due to EZH2’s non-catalytic functions, which remain active despite inhibition of its methyltransferase activity." (PMID 40872531, 2025). "Given that USP7 is responsible for stabilizing EZH2 and ERα, it is interesting to consider how USP7 might regulate inflammation by exploiting EZH2 stabilization based on the presence or absence of ER in breast cancer." (PMID 39767641, 2024). "Therefore, we initially compared the expression level of EZH2 and G9a in noncancerous mammary epithelial cells (MCF10A) and multiple cell lines from breast cancer (MCF7, BT549, and MDA-MB-231), colon cancer (SW480 and HCT116), and prostate cancer (PC3 and DU145)." (PMID 35409271, 2022). "As breast cancer is a heterogeneous disease which could be grouped into Luminal A, Luminal B, HER2-enriched, and Triple negative subtypes, we further explored the relationship of EZH2 and STAT3 expression with survival of patients in breast cancer subtypes." (PMID 34335938, 2021).
prostate carcinoma (524 papers, 2005 to 2026). A carcinoma that arises from epithelial cells of the prostate gland. "Our current article identifies EZH2 as a master regulator to reshape the global m6A methylome in prostate cancer cells and uncover the underlying mechanism." (PMID 41252201, 2026). "Prior work demonstrates KRAS or MAPK activation is linked with prostate cancer aggressiveness, and this is explained in part by EZH2-mediated suppression of the negative regulator of Ras59,60." (PMID 40624104, 2025). "High expression of EZH2 was also correlated with high risk of recurrence of prostate cancer after radical prostatectomy." (PMID 40959108, 2025). "This review comprehensively systematically examines the molecular mechanisms underlying the SETD2/EZH2 axis in prostate cancer, providing a theoretical foundation for developing precision therapies based on SETD2- or EZH2-mediated epigenetic modifications." (PMID 40959108, 2025). "Evidence suggests that high expression of EZH2 is associated with a higher risk of recurrence of metastatic disease after radiation therapy, and is involved in promoting the radioresistance of prostate cancer cells." (PMID 40028035, 2025). "For instance, EZH2‐mediated H3K27me3 silencing is associated with aggressive tumor behavior and resistance to therapy in breast and prostate cancers." (PMID 40959208, 2025). "In prostate cancer research, hypoxia-induced EZH2 causes hypermethylation of the TGFBR2 promoter, reducing its expression." (PMID 40427283, 2025). "EZH2 overexpression was one important cause of docetaxel and enzalutamide resistance in prostate cancer." (PMID 40959108, 2025). "EZH2 has been identified as a key player in cancer development and progression with its first reported involvement in oncogenesis linked to prostate cancer in 2002, by Varambally and colleagues." (PMID 40004468, 2025). "In prostate cancer, numerous genes have been identified as direct EZH2 targets and are associated with cancer progression and metastasis in the silenced state, which further confirms that EZH2 is a true oncogene." (PMID 40959108, 2025). "The significance of EZH2 in cancer was first realized in 2002 when Varambally and colleagues elucidated the association between EZH2 and prostate cancer prognosis." (PMID 40028035, 2025). "We and others have recently implicated the role of EZH2 in regulating NE phenotype in prostate cancer cells." (PMID 38777812, 2024). "In a study on prostate cancer, elevated levels of EZH2 and H3K27me3 were associated with poor prognosis in metastatic prostate cancer." (PMID 36672374, 2023). "We showed that INPP4B knockdown causes a decrease in EZH2 levels in two independent prostate cancer cell lines, LNCaP and VCaP." (PMID 38001678, 2023). "In prostate cancer specimens, EZH2 expression was inversely linked to miR-124-3p in the current study." (PMID 36884182, 2023). "Histone modification-related enzymes thought to be associated with prostate cancer progression include histone methyltransferase EZH2, lysine-specific demethylase 1 (LSD1), histone methyltransferase SET9, and others." (PMID 37190171, 2023). "For example, treatment with EZH2 inhibitors in various in vitro and in vivo prostate cancer models of PTEN and RB1 loss sensitized cells and tumors to enzalutamide." (PMID 36212399, 2022). "EZH2 is overexpressed in numerous tumor entities, including neuroblastoma, small cell carcinoma, and prostate cancer, and is frequently associated with aggressive disease, leading to its classification as an oncogene." (PMID 35013218, 2022). "Intracellular delivery of miRNA-124 reduces AR splice variants and suppresses EZH2 as a downstream target to prevent prostate cancer progression." (PMID 35236381, 2022). "SKP2 knockdown inhibits EZH2 expression prostate cancer cells by promoting TRAF6-induced K63-linked ubiquitination of EZH2 for degradation." (PMID 36202787, 2022).